INS (insulin)
Diseases named in the same sentence as INS in open-access papers (continued):
Sharing a sentence is not in itself a finding about the gene and the disease.
Insulin resistance (continued). "Smoking causes inflammation, tissue damage, insulin resistance, reduced insulin secretion, endothelial dysfunction, impaired lipid and glucose metabolism, and beta-cell toxicity." (PMID 40507369, 2025). "Skeletal muscle is responsible for approximately 60–80% of glucose uptake following a meal in response to insulin, emphasizing its key role in insulin resistance associated with type 2 diabetes." (PMID 40573101, 2025). "Loss of insulin signaling due to the selective deletion of the insulin receptor in hepatocytes leads to glucose intolerance associated with severe insulin resistance and strong hyperinsulinemia." (PMID 40228209, 2025). "Insulin resistance contributes to the development of hypertension as well because it impairs the vasodilator effect of insulin and causes vasoconstriction as a result of free fatty acids." (PMID 39817379, 2025). "Elevated intake of AAAs has been associated with impaired insulin signaling and reduced glucose clearance, contributing to insulin resistance and a higher risk of GDM." (PMID 39796608, 2025). "Obesity is also frequently associated with insulin resistance and hyperinsulinemia, whereby insulin and related growth factors promote tumor growth by enhancing cellular proliferation and inhibiting apoptosis." (PMID 41299673, 2025). "Insulin resistance is a fundamental issue associated with the disorder, wherein cells in the adipose tissue, liver, and muscle resist the action of insulin, leading to dysregulation of glucose metabolism." (PMID 40896083, 2025). "In insulin-resistant adipocytes, elevated levels of ganglioside GM3 disrupt the IR-Cav-1 complex, leading to reduced insulin sensitivity and contributing to adipose tissue insulin resistance, a hallmark of metabolic syndrome." (PMID 40358155, 2025). "Phosphatidylethanolamines, phosphatidylinositols, and phosphatidylcholines, were strongly associated with insulin resistance, while plasmalogens and sphingomyelins were consistently linked to insulin sensitivity." (PMID 40422918, 2025). "Diets with a high insulin index, load, and glycemic index are thought to increase BC risk by promoting hyperinsulinemia and insulin resistance, conditions linked to cancer development." (PMID 39940252, 2025). "Accordingly, loss-of-function mutations in PTEN can enhance insulin signaling in different organs, leading to protection against insulin resistance, a critical pathogenic process in NAFLD and T2DM." (PMID 40311678, 2025). "Vitamin D is recognized for its role in regulating insulin secretion, and deficiency has been linked to the development of insulin resistance and glucose intolerance." (PMID 39999040, 2025). "In turn, insulin resistance or DM can further disrupt the mitochondrial metabolism, causing reduced insulin secretion from pancreatic β-cells, enhanced mitochondrial permeability transition, or increased mitochondrial apoptosis." (PMID 41394217, 2025). "PCOS is commonly associated with insulin resistance (IR), a term used to describe a decrease in the cellular response to insulin signaling which subsequently induces an increase in insulin secretion." (PMID 39959624, 2025). "Insulin resistance (IR) refers to the decreased/weakened response of target tissues to insulin that causes disorders of glucose and lipid metabolism." (PMID 41473239, 2025). "This increase in myonectin levels was also associated with significant changes in fasting insulin and insulin resistance." (PMID 40134450, 2025). "Alterations in lipid metabolism, such as increased free fatty acids and the accumulation of lipid intermediates, cause insulin resistance by interfering with insulin signaling pathways." (PMID 41514592, 2025). "In the case of sarcopenia, the alteration of insulin sensitivity‐regulating myokine secretion, and lipids accumulating in muscle tissue induces insulin resistance, which was associated with overall and cancer‐specific survival." (PMID 39797562, 2025).
Insulin resistance (continued). "Higher mtDNA DAMP levels were independently associated with increased insulin resistance and decreased insulin sensitivity in adults with type 2 diabetes." (PMID 41156500, 2025). "T2D represents 90% to 95% of all cases and is commonly associated with obesity and physical inactivity, leading to insulin resistance and an eventual reduction in insulin production." (PMID 40429748, 2025). "This elevated expression is associated with postprandial hyperglycemia, insulin resistance, and elevated circulating insulin levels." (PMID 40862720, 2025). "Together with age-related gradual peripheral mitochondrial dysfunction, accumulated injury results in the gradual development of insulin resistance as well as a gradual loss of insulin responsiveness." (PMID 39561140, 2024). "Insulin resistance causes cells to become less sensitive to insulin as well as instigating changes in glucose metabolism (e.g., uptake or storage)." (PMID 39539361, 2024). "In this study, we found that seropositivity to HAdv-D36 was not related to nutritional status; however, individuals previously infected by the virus had lower insulin levels and a lower risk of insulin resistance." (PMID 38932286, 2024). "A HFD causes obesity in rats and increases glucose and insulin tolerance, leading to insulin resistance." (PMID 39458511, 2024). "As with enfortumab vedotin, the 3 cases of brentuximab vedotin–associated DKA were associated with severe insulin resistance, with insulin requirements up to 10 725 units per day in one case." (PMID 39588551, 2024). "Though the loss of insulin activity and low production of insulin from pancreatic beta-cells are the metabolic markers that characterize T2D, obesity and insulin resistance are the most common causes of T2D." (PMID 39885962, 2024). "In type 2 diabetes (T2D), insulin resistance, resulting from multiple causes, leads to increased insulin secretion to control blood sugar." (PMID 39072276, 2024). "T2DM, is characterized by a progressive loss of insulin sensitivity, commonly referred to as insulin resistance." (PMID 38658944, 2024). "Sustained high fat intake for > 3 weeks causes a loss of CEACAM1 by > 60%, at which point, insulin clearance is impaired and hepatic insulin resistance develops preceding inflammation." (PMID 39640841, 2024). "T2D is preceded by a latent period, known as prediabetes, which is caused by peripheral insulin resistance and a compensatory increase in circulating levels of insulin; almost one in three individuals in the United States in 2020 had insulin resistance." (PMID 38959440, 2024). "The two metabolic changes that lead to pre-diabetes and type 2 diabetes developments are insulin resistance and deficient insulin secretion." (PMID 38732139, 2024). "A hallmark of T2DM is insulin resistance (IR), characterized by decreased sensitivity of insulin target organs, notably skeletal muscles, crucial for glucose uptake and metabolism." (PMID 39596482, 2024). "This study found that elevated fasting insulin levels or insulin resistance, quantified using HOMA-IR, correlate with an increased risk of hypertension in the general population." (PMID 38711979, 2024). "A recent study showed that ER stress originates in individuals with insulin resistance associated with beta cell work overload, with concomitant defects in insulin processing and loss of beta cell identity." (PMID 38864887, 2024). "It is true that obese individuals are at high risk for T2D development as they release more insulin after consuming glucose, which often leads to impaired pancreatic β -cell function and insulin resistance." (PMID 38613048, 2024). "The association between glucose levels, insulin, C-peptide, insulin resistance indices, and beta-cell function indices with FIB-4 was analyzed only for non-diabetic subjects with fasting glucose levels below 110 mg/dL." (PMID 39518569, 2024).
Insulin resistance (continued). "Phosphorylation of protein kinase B (Ser473 and Ser474) was found in mice fed with BCAAs, which can block normal insulin signaling and cause insulin resistance." (PMID 38868299, 2024). "The primary pathophysiological features of T2MD are impaired insulin secretion and insulin resistance, with insulin resistance being the principal cause of T2MD." (PMID 38915894, 2024). "Weight loss has an immunomodulatory effect, insulin resistance was reversed, blood insulin and BP decreased, and blood hemoglobin increased." (PMID 38744929, 2024). "Regular physical exercise enhances muscle glucose uptake and increases the expression of GLUT4, a glucose transporter, in muscle cells, thereby improving insulin sensitivity and reducing the risk of developing insulin resistance and T2D." (PMID 39337980, 2024). "One explanation is that MASLD is closely associated with insulin resistance and the resulting failure of insulin to lower circulating blood glucose masks any lowering effect of glucagon signalling deficiency on glucose levels." (PMID 38579751, 2024). "Due to the coexistence of both insulin resistance and the loss of endogenous insulin production, insulin resistance in T1DM is frequently referred to as “double diabetes”." (PMID 39768947, 2024). "The mother secretes more insulin to maintain normal blood glucose levels due to the decrease in insulin sensitivity caused by the increase in hormones, resulting in significant insulin resistance." (PMID 39876919, 2024). "Diabesity involves both genetic and environmental factors and manifests as a connection between two metabolic disorders characterized by defects in cellular insulin, whose sensibility is primarily attributed to insulin resistance and insulin deficiency." (PMID 38921462, 2024). "Hyperinsulinemia and insulin resistance are directly linked to HT because insulin raises sympathetic activity in the autonomic nervous system and lowers prostaglandin production in adipose tissue." (PMID 39459569, 2024). "Insulin resistance and subsequently increased insulin levels are linked to heightened FMO3 activity, which in turn leads to elevated levels of TMAO." (PMID 39092284, 2024). "Beyond inflammation, the STING-IRF3 pathway has been implicated in the dysregulation of insulin signaling, which is a key feature of obesity-related insulin resistance." (PMID 39669992, 2024). "“Normal” age-related changes and/or progression in insulin resistance are likely to further alter blood flow and its association with glucose metabolism and place younger insulin resistant individuals at risk for cognitive decline." (PMID 38914735, 2024). "The presence of high levels of long-chain Acyl-CoAs and other fatty acid metabolites in muscle and heart tissue is associated with a decline in insulin signaling and the development of insulin resistance (IR)." (PMID 39085907, 2024). "Prior studies reported that these biomarkers were inversely associated with some metabolic abnormalities such as insulin resistance (IR) and dyslipidemia, through their involvement in energy hemostasis and insulin response." (PMID 38409315, 2024). "Metabolic syndrome results from complex dysregulation of metabolic homeostasis in tissues including liver, adipose tissue, muscle and intestine and is associated with reduction of insulin signaling and action, i.e., insulin resistance." (PMID 39532838, 2024). "The prediction of type 1 diabetes risk was consistent with the staging findings: after adjusting for insulin secretion, type 1 diabetes occurrence was associated with high insulin resistance and low insulin sensitivity." (PMID 37914981, 2024). "It is important to mention that some studies have indicated that feeding mice with HFD containing 60 % lard for 3, 6, or 12 months can cause insulin resistance and increased plasma insulin levels." (PMID 38975085, 2024).
Insulin resistance (continued). "Foods high in glycemic index require insulin in large amounts, which over time can hinder the activity of insulin receptors making them less responsive and causing insulin resistance." (PMID 39363272, 2024). "Our study evaluated HOMA-IR and measured fasting insulin and found that both variables were positively associated with BF%, suggesting that insulin resistance increases with increasing fat percentage." (PMID 39328456, 2024). "The reduced ability of insulin to activate the GLUT4 glucose transport system in skeletal muscle is a primary cause of insulin resistance." (PMID 38397782, 2024). "Type 2 diabetes (T2DM), associated with insulin resistance or inadequate insulin production, is increasing globally, with urgent public health measures warranted." (PMID 38978922, 2024). "Higher serum myostatin levels were associated with lower insulin sensitivity by Matsuda index and higher insulin resistance by HOMA‐IR, which remained significant after controlling for sex (p = 0.04 and p = 0.03, respectively)." (PMID 39261976, 2024). "It is closely linked to insulin resistance, a condition where body cells fail to respond adequately to insulin, eventually leading to insufficient insulin production for the body’s needs." (PMID 39335472, 2024). "Studies have shown that hybrid receptors have reduced insulin affinity compared to the IR and have been associated with metabolic and mitogenic dysregulated diseases, such as insulin resistance and certain types of cancer." (PMID 39572596, 2024). "The main disease associated with insulin resistance and alterations of the insulin cardiac axis is diabetic cardiomyopathy, particularly pathological cardiac hypertrophy." (PMID 39125938, 2024). "Weight loss has been shown to increase SHBG, lower free androgens, and improve cardiometabolic risk factors including insulin, insulin resistance, and cholesterol levels." (PMID 38446316, 2024). "Insulin resistance in 7CafD females was associated with a reduced expression of insulin signalling and glucose transport genes in all metabolic tissues: Insr and Irs2 in liver, Insr and Slc2a4 in WAT, and Slc2a4 in muscle." (PMID 39596499, 2024). "Patients with diagnosed insulin resistance associated with generalized lipodystrophy or mutations in insulin receptors require higher doses of insulin." (PMID 38397072, 2024). "While T2DM, which represents 85–95% of all cases, is associated with insulin resistance (IR) within insulin-responsive tissues as well as a decline in insulin production from pancreatic β cells." (PMID 38698488, 2024). "These genetic variants are often found in genes involved in insulin secretion, insulin resistance, and glucose metabolism pathways." (PMID 38694942, 2024). "Depression is also associated with insulin resistance, an underlying, defining characteristic of type 2 diabetes in which the body loses sensitivity to insulin, leading to elevated blood glucose." (PMID 39579357, 2024). "Obesity can also lead to endocrine abnormalities, such as insulin resistance and abnormal insulin secretion, and these factors are also associated with the development and recurrence of AF." (PMID 38707891, 2024). "The pathophysiology of T2DM starts from insulin resistance with relative insulin deficiency to an insulin secretion defect with insulin resistance." (PMID 39063010, 2024). "QG promoted Akt phosphorylation in the association of insulin, even when palmitic acid was administered to mature myoblasts, indicating its potential to mitigate palmitic acid-induced insulin resistance." (PMID 38474775, 2024). "Obese or pubertal children usually require more insulin due to increased insulin resistance, while younger children need less, given their lower body weight, higher insulin sensitivity, and hypoglycemia risk." (PMID 38590482, 2024). "Proinflammatory factors cause insulin resistance by interfering with insulin signaling pathways, thereby increasing the risk of GDM." (PMID 39655348, 2024).
Insulin resistance (continued). "In this context, increased leptin level, a common finding in obesity, is strongly associated with insulin resistance partially through increased adiposity, which suggests an overall decrease in sensitivity to leptin and insulin in obesity." (PMID 38289144, 2024). "Trigonelline has been shown to elicit several antidiabetic effects, including improving β-cell function and insulin secretion, while also attenuating oxidative stress, hyperglycemia, insulin resistance, diabetic nephropathy, and diabetic hearing loss." (PMID 39201652, 2024). "MetS increases the risk of developing type 2 diabetes and insulin resistance because cells become less responsive to the effects of insulin." (PMID 38971308, 2024). "Higher insulin levels observed in gallstone patients suggest that insulin resistance is a significant risk factor for the formation of gallstones." (PMID 39104753, 2024). "Conversely, metabolic syndrome and insulin resistance are linked to obesity-related CRC through alterations in insulin and the IGF system." (PMID 39201522, 2024). "In a multivariate model including myostatin, BMI, VAT, ALM, and sex, myostatin remained significantly negatively associated with insulin sensitivity by Matsuda index (p = 0.04) and insulin resistance by HOMA‐IR (p = 0.04)." (PMID 39261976, 2024). "SCA has been associated with insulin resistance, a condition in which cells respond less effectively to insulin." (PMID 38669382, 2024). "TNF-α, which is overexpressed by adipocytes under conditions of insulin resistance and the hypertrophy of adipose cells, causes insulin resistance by interfering with the transmission of the insulin signal and activating inflammation processes." (PMID 39125666, 2024). "The release of pro-inflammatory cytokines mediated by immune cells interferes with insulin signaling pathways, causing insulin resistance, which then affects blood glucose and the endocrine system." (PMID 39623450, 2024). "In fact, increased hepatic lipid droplet content has been associated with steatosis and insulin resistance, whereby lipid droplets physically interact with stress kinases, inhibiting insulin signalling activation and blocking glucose uptake." (PMID 38383863, 2024). "Insulin resistance, caused by the inhibition of insulin signaling, triggers a series of immune responses that exacerbate the inflammatory state, leading to hyperglycemia." (PMID 38468345, 2024). "Insulin dysregulation in horses is characterised by hyperinsulinaemia and/or tissue insulin resistance and is associated with increased risk of laminitis." (PMID 38412155, 2024). "While these findings need to be confirmed through further larger and expanded studies, this investigation indicates a new potential role of zinc status and its significant associations with indexes of insulin sensitivity and insulin resistance." (PMID 39596259, 2024). "Obesity-mediated liver inflammation is also attenuated with reduced interleukin (IL)−12, a cytokine primarily released by macrophages, and IL-12 treatment in vivo causes insulin resistance by impairing hepatic insulin signaling." (PMID 38951527, 2024). "Hyperglycemia, the deficiency of intrinsic insulin or insulin resistance increases platelet reactivity due to the loss of inhibition of P2Y12 by the insulin-related pathway." (PMID 39092013, 2024). "Both of these alterations associated with obesity can detrimentally affect insulin function, thereby establishing a probable link between obesity and insulin resistance." (PMID 38317257, 2024). "And adipocytokines produced by abdominal fat itself, such as leptin and adiponectin, disturb the insulin signaling pathway and cause insulin resistance." (PMID 40777932, 2024). "Although most studies suggest that BCAAs improve insulin sensitivity, there is some experimental evidence that high circulating levels of BCAAs are associated with insulin resistance and other metabolic disorders." (PMID 39456742, 2024).